TNF (tumor necrosis factor)
Diseases named in the same sentence as TNF in open-access papers (continued):
Sharing a sentence is not in itself a finding about the gene and the disease.
migraine (continued). "Consistent with this view, we found that the stimulation of meninges with the P2X7 agonist BzATP enhanced the release of the pro-inflammatory TNFα and Il-10, which are both implicated in migraine pathology." (PMID 35614095, 2022). "In a Jordanian population of 198 migraine patients and 200 controls, there was a significant association with two SNPs regarding TNF-α gene." (PMID 35432179, 2022). "In migraine patients, increased plasma levels of IL-10, TNFα, and IL-1 beta have been observed after a migraine attack and some studies have linked migraine attacks to local inflammatory events." (PMID 34948222, 2021). "In recent studies, high serum levels of IL-1β, IL-6, and TNF (proinflammatory cytokines) in patients with migraine indicated that migraine was associated with inflammation within peripheral endings of trigeminal ganglion sensory neurons." (PMID 33995549, 2021). "Histamine, leukotrienes, TNF-alpha, IL-6 and endothelin-1 released from MCs have been implicated in the pathophysiology of migraines." (PMID 33673856, 2021). "Accordingly, in the present study, we reported that the decrease in CGRP plasma levels and gene expression was associated with a significant reduction of TNF-alpha and IL-6 gene expression in peripheral and central areas involved in migraine pain." (PMID 34685523, 2021). "We found that, among patients with RA, the use of TNF-alpha inhibitors was associated with an elevated risk of migraine." (PMID 32560321, 2020). "First, patients who used TNF-alpha inhibitors had highly active disease, and our results tended to show that high disease activity was associated with migraine occurrence." (PMID 32560321, 2020). "sCD40L stimulates the production of proinflammatory cytokines (IL-1, IL-6, IL-8, IL-10, TNF), which are pain mediators and are suggested to be implicated in neurovascular inflammation resulting in migraine pain." (PMID 33020432, 2020). "TNF-alpha blockade treatment was associated with a significantly higher risk of migraine (OR = 1.90, 95% CI: 1.13–3.25)." (PMID 32560321, 2020). "The pain of migraine-associated headaches has been linked to the activation of nociceptors by the vasoconstriction-inducing cytokines TNF and IL-1." (PMID 31781229, 2019). "Among the 11 papers focusing on TNF –308G>A, 7 reported genotype and allele frequencies for all participants and for overall migraine, as well as stratified by gender and aura; however, the remaining 4 papers did not." (PMID 26098763, 2015). "Due to the failure of independent association studies in identifying a role for the TNF –308G>A polymorphism in migraine, two meta-analyses were performed to reach definitive and reliable conclusions." (PMID 26098763, 2015). "In this research, we have identified significant differences between MM cases and controls, which both show increased risk of migraine development for the G alleles in the tested SNPs in the TNF and SYNE1 genes." (PMID 25315199, 2014). "TNF-β is another subunit of TNF gene and has been frequently investigated in the studies concerning migraine risk." (PMID 24959879, 2014). "TNF-α, a potential pain mediator in neurovascular inflammation, has been reported to increase migraine risk in the population of Italian ancestry." (PMID 24959879, 2014). "Multiple neurotransmitters and hormones, including CGRP, substance P, neuropeptide Y, adiponectin, leptin, orexin-A, interleukin (IL)-1, IL-6, and TNF-α have been implicated in migraine pathogenesis." (PMID 23181051, 2012). "This review of randomized trials highlights that elevated serum cytokines (particularly IL-1β, IL-6, and TNF-α) are associated with increased migraine frequency and may contribute to migraine chronification." (PMID 41377228, 2025). "An IgG-positive food elimination diet improved migraine and its comorbidities and reduced IL-6, TNF-α, and CGRP, which might be associated with the alleviated systemic chronic inflammation and downregulation of the sensitivity of trigeminal nerve endings." (PMID 41473187, 2025).
migraine (continued). "Moreover, the KD reduces oxidative stress and downregulates pro-inflammatory cytokines such as TNF-α and NF-κB, both of which are implicated in migraine pathogenesis." (PMID 40426647, 2025). "However, upon adjusting for variables such as DBP and TNFα, the previously observed association between the genetic predisposition to migraine and AD risk dissipated." (PMID 38903170, 2024). "Several cytokines, including TNFα, IL-1, and IL-6, are implicated in the pathogenesis of migraine." (PMID 38903170, 2024). "It has been reported that proinflammatory factors, such as TNF-α and IL-1β, may be associated with the release of neuro-mediators of pain in the migraine initiation." (PMID 37460956, 2023). "In patients with gout, the deposition and phagocytosis of monosodium urate crystals in tissues activate the NLRP3 inflammasome, leading to the production of critical cytokines such as IL-1β, IL-6, and tumor necrosis factor (TNF)-α, which are implicated in the occurrence of migraines." (PMID 38202145, 2023). "Therefore, we aim to provide a glimpse of the association of the TNF-α 308G > A risk on the susceptibility of migraine." (PMID 37085790, 2023). "Results obtained from animal models of headache also support that immunological responses associated with cytokines are involved in the mechanism of migraine, including enhanced production of several inflammatory cytokines, such as IL-1β, IL-6, and TNF-α during CSD." (PMID 37287623, 2023). "Animal and human studies suggest that TNF-α contributes to the pathogenesis of migraine, and that its secretory capacity might be regulated by a gene variant in the promoter region of the TNF gene." (PMID 37176049, 2023). "Our group previously reported that the –308 G allele of TNF-α was associated with migraine." (PMID 36614097, 2022). "Non-steroidal anti-inflammatory drugs (NSAIDs) have long been used in treating migraine attacks, so that multiple cytokines, such as IL-1β, tumor necrosis factor (TNF), and IL-6, have been associated with the pathogenesis of migraine, as their levels are altered in migraine patients." (PMID 36247795, 2022). "Various cytokines, including tumour necrosis factor (TNF), interleukin 1 (IL-1) and adiponectin, have been implicated in inflammation, modulation of the pain threshold, trigeminal nerve fiber sensitization, and ultimately the precipitation of migraine." (PMID 34112082, 2021). "Additionally, proinflammatory cytokines, including IL-1β, IL-6, IL-8, and TNF-α have been implicated in migraine pain and are increased during migraine attacks." (PMID 32054443, 2020). "Cytokine Polymorphism (TNF-α and IL-1β gene polymorphisms) in patients with migraine without aura provide some more suggestive evidence for a possible contribution of inflammation in migraine." (PMID 30974836, 2019). "In addition, we examined several other molecules putatively involved in migraine pathophysiology: SP, IL-1β, IL-6 and TNF-α which have all been shown to be associated with activation of the trigeminovascular system." (PMID 28337634, 2017). "Specifically, there were moderate to high degrees of heterogeneity among the studies investigating the association of the TNF –308G>A polymorphism with migraine and MO, which may have been due to differences between subgroups." (PMID 26098763, 2015). "Our findings appear to support the hypothesis that genetic variability of 252A>G polymorphism in TNF region may modulate risk of migraine in the population of Asian ancestry." (PMID 24959879, 2014). "Also some studies showed a relationship between migraine and inflammatory cytokine polymorphisms such as TNF-α-308G/A." (PMID 23984350, 2013). "They revealed that the TNF-alpha −308G/A polymorphism was associated with migraine risk." (PMID 23984350, 2013). "The authors suggested that if TNF-alpha plays a role in migraine physiopathology, migraine patients may lack sufficient antagonistic sTNF-RI to neutralize hyperalgesic TNF-alpha during a migraine attack, causing pain." (PMID 19018300, 2008).
migraine (continued). "Besides, headaches are more frequent after the second vaccination of mRNA vaccines, CD4 + T-cell expresses with Th1 cytokines like TNF-α, which can sensitize meningeal nociceptors and stimulate the synthesis of the migraine-associated calcitonin gene-related peptide." (PMID 38431578, 2024). "However, genetic predisposition in the genes of the inflammatory system might be the cause for CI and TNF-α is the prime candidate which is seen to be higher in the subjects of migraine." (PMID 38213956, 2024). "Furthermore, in 2024, the Hautakangas team conducted a meta-analysis of three GWAS studies on migraine, confirming multiple risk loci, including TNF-α, MRPS21, and SELENBP1, which are closely linked to inflammatory responses, mitochondrial function, and oxidative stress." (PMID 39850553, 2024). "Additionally, these fatty acids help rebalance vital neurotransmitters, such as serotonin and dopamine, essential for the functioning of the trigeminovascular nociceptive pathway, and can inhibit TNF-α expression, potentially reducing cerebral vasodilation implicated in migraine episodes." (PMID 38770523, 2024). "Thus, it is suggested that Pyk2 may modulate neuroinflammation in migraine in association with TNF-α." (PMID 37176049, 2023). "Also associated with migraine episodes are up-regulated inflammatory platelet and white blood cell (leukocyte) aggregates as well as cytokines (e.g., interleukins 1, 6, and 8 and tumor necrosis factor-α); altered nitric oxide concentrations have also been found during MH attacks." (PMID 28373854, 2017). "Antibiotic treatment prolongs migraine‐like pain in wild‐type mice, but genetic deletion of TNF‐α or intraspinal injection of a TNF‐α receptor antagonist prevents pain prolongation." (PMID 40908772, 2025). "Studies have shown that changes in the composition of the gut microbiota and related metabolites, such as short-chain fatty acids (SCFAs), and the release of cytokines, such as TNF-α, can modulate migraine-like pain in animal models." (PMID 40395547, 2025). "A recent study found that cytokine levels, including IL-4, TNF-α, IL-17A, and IL-12p70, are elevated in children with migraine." (PMID 40149800, 2025). "A meta-analysis revealed that serum levels of CRP, IL-1β, IL-6, and TNF-α were elevated in migraine patients compared to healthy controls." (PMID 40149800, 2025). "A recent meta-analysis found significantly higher circulating levels of C-reactive protein (CRP), IL-1β, IL-6, and TNF-α in patients with migraine relative to healthy individuals." (PMID 41377228, 2025). "Our preliminary findings suggest a potential role for peripheral inflammatory markers, including specific microRNAs (miR-197, miR-101, and miR-143) and cytokines (TNF-α, IL-6, and IL-17A), in the pathophysiology of migraine." (PMID 41010614, 2025). "Pro-inflammatory cytokines, such as interleukin (IL)-1β, IL-6, and tumor necrosis factor (TNF)-α, rise during migraine attacks, sensitizing pain pathways and increasing gut permeability, worsening neuroinflammation." (PMID 40230722, 2025). "Previous reports, demonstrated acute NTG-induced mast cell inflammation and increases in proinflammatory cytokines like TNF-α and IL-1β in the colon, providing critical groundwork for GI involvement in migraine." (PMID 41226532, 2025). "The water extract significantly reduced the levels of inflammatory factors such as NO and IL-6 in the serum of migraine rats; ethanol extract inhibited TNF-α secretion of macrophages." (PMID 41020864, 2025). "TNF-α and IL-6 are classic pro-inflammatory cytokines that have been widely investigated in many migraine studies." (PMID 41473187, 2025). "In a study, researchers found that in a mouse model of migraine induced by nitroglycerin, there was a significant increase in inflammatory factors such as TNF-α and IL-1β in the colon and a decrease in the integrity of the colonic epithelial barrier." (PMID 40143202, 2025).
migraine (continued). "Patients with chronic or frequent migraines tended to have higher pro-inflammatory cytokine levels (IL-6 and TNF-α) compared to those with episodic/less-frequent migraines." (PMID 41377228, 2025). "Neurogenic neuroinflammation has a wide role in migraine pathogenesis, with altered systemic immune responses occurring in migraine patients due to the release of pro-inflammatory cytokines, such as TNF-α and IL-6, both in ictal and interictal periods." (PMID 41473187, 2025). "The difference in the change of “days with migraine in past 4 weeks” between the sham and true diet groups was significantly attenuated after adjusting for IL-6 and TNF-α." (PMID 41473187, 2025). "Plasma cytokine levels have been studied previously in primary headache disorders, with higher levels of pro-inflammatory cytokines IL-6, IL-8, TNF-⍺, and IL-1β reported in migraine compared to healthy controls." (PMID 40991059, 2025). "The “leaky gut” can lead to elevated levels of proinflammatory cytokines like TNF‐α, IL‐1β, and IL‐6, which can influence nociceptive responses and trigger migraine headaches." (PMID 40908772, 2025). "Inhibition of PD-1 amplified migraine-induced hyperalgesia was accompanied by increased calcitonin gene-related peptide, interleukin-1β, tumor necrosis factor α, interleukin-6, and interleukin-18 in the trigeminal ganglia of mice." (PMID 40002809, 2025). "Proinflammatory cytokines, including IL-1β, IL-6, IL-8, and TNF-α, are elevated during migraine attacks, sensitizing nociceptive pathways such as the trigeminal system." (PMID 40175732, 2025). "TNF-α, a key mediator of neuroinflammation, can induce pain hypersensitivity and has been shown to correlate with migraine likelihood." (PMID 41377228, 2025). "TNF-α is another prime candidate; it was significantly elevated in migraine patients vs controls in multiple studies and is biologically plausible in driving headache frequency (by promoting CGRP release, neurogenic inflammation, and central sensitization)." (PMID 41377228, 2025). "Obesity is connected to increased levels of proinflammatory cytokines, such as IL-6 and TNF-alpha, and adipokines like leptin, which are known to activate the trigeminovascular pathways that play a role in migraines." (PMID 41278056, 2025). "In summary, we provide clinical evidence that the IgG-positive food elimination diet was beneficial to migraine and its comorbidities and reduced the production of IL-6, TNF-α, and CGRP." (PMID 41473187, 2025). "Elevated levels of inflammatory cytokines, such as IL-6, TNF-α, and CGRP, are implicated in pain transmission and vascular changes during migraine episodes." (PMID 40426647, 2025). "Based on this review, IL-6, IL-1β, and TNF-α stand out as the most plausible biomarkers for migraine chronification." (PMID 41377228, 2025). "In migraine, activation of the immune-neurological system occurs, resulting in the release of pro-inflammatory cytokines such as tumor necrosis factor-alpha and interleukins, especially interleukin-1 beta and interleukin-6." (PMID 40427393, 2025). "Pro-inflammatory cytokines – such as IL-1β, IL-6, IL-8, and TNF-α – are often elevated interictally in migraineurs compared to non-migraine controls." (PMID 41377228, 2025). "On the other hand, during migraine attacks, there is an increase in the release of pro-inflammatory cytokines such as IL-1β, IL-6, and TNF-α." (PMID 39107712, 2024). "Such that, the secretion of inflammatory cytokines, such as tumor necrosis factor-α (TNFα), would lead to neuroinflammation and migraine episodes by increasing the cellular permeability and interactions." (PMID 39539367, 2024). "Previous studies have suggested that inflammatory reactions play a certain role in the occurrence and development of adult migraine or animal models, which are most on the pro-infammatory, such as cytokines IL-1β, IL-6, TNF-α, and CGRP unfolded." (PMID 38356891, 2024).
migraine (continued). "Even aggressive interventions fail to alleviate the condition when TNF-α levels in the cerebrospinal fluid of migraine patients are elevated but normal in the blood." (PMID 39416954, 2024). "Interleukin 1β and tumor necrosis factor alpha, well-established players in the pathophysiology of migraine, are often elevated in the serum of migraine sufferers." (PMID 38731144, 2024). "As a result, it is obvious that neurogenic neuroinflammation plays a substantial role in migraine pathogenesis and that microglial activation plays a vital role in disease development in terms of TNF-α signaling." (PMID 38213956, 2024). "The secretion of inflammatory cytokines, such as tumor necrosis factor (TNF)-a, would lead to neuroinflammation and migraine episodes by increasing the cellular permeability and interactions." (PMID 39539367, 2024). "In the ACC, the expression levels of IL-1β, IL-6, and TNF-α were higher in the NTG-induced migraine groups than in the VEH group; proinflammatory cytokine expression was significantly higher in the CM group than in the EM group." (PMID 38612517, 2024). "For a long period, TNF-α is the primary candidate when linking neurogenic neuroinflammation and migraine." (PMID 38213956, 2024). "In contrast to the evidence implicating TNF-a in the pathogenesis of migraine and our findings here, many people have received anti-TNFα treatment, and no change in migraine symptoms has been reported in these patients." (PMID 38802819, 2024). "In conclusion, serum levels of IL-4, TNF-α, IL-17A, and IL-12p70 are increased in children with migraine." (PMID 38356891, 2024). "The results suggested that TNF-α exerted a harmful effect on the onset of headache in children, especially the attack of migraine, which was consistent with previous studies." (PMID 38356891, 2024). "For example, propionate and butyrate reduced the onset of pain in a nitroglycerine-induced mouse model of migraine and reduced the release of IL-1β and TNF-α in the ileum." (PMID 38690367, 2024). "Concerning the expression analysis, Taheri and colleagues, after utilizing the expression assays for finding the expression level of cytokines in migraine sufferers compared to healthy controls, observed increased TNF-α expression inpatients than controls." (PMID 38213956, 2024). "In fact, TNF-α presence is commonly increased in the plasma, serum, and/or urine during migraine attacks and attack-free intervals, suggesting the pathogenic role of TNF-α in the inflammatory state of these patients." (PMID 38397400, 2024). "Taking TNF-α as a reference point, various disorders have been discovered to be comorbid with migraine." (PMID 38213956, 2024). "The results indicated increased expression of proinflammatory cytokines (IL-1β, IL-6, and TNF-α) in the Sp5C regions of NTG-induced migraine groups compared with the VEH group; expression levels were significantly higher in the EM group than in the CM group." (PMID 38612517, 2024). "Interictally, migraine patients have higher interleukin (IL)-1β, IL-6, TNF-α, IL-8, IL-12p70 and CCL3 and lower IL-10 levels." (PMID 38913047, 2024). "Li Jinhong found that the levels of serum INF-α, IL-2, IL-17, IL-12P70, TNF-α, IL-5, IL-1β, and IL-4 were higher in adult migraine patients than in normal control group, which changed with different stages of the disease." (PMID 38356891, 2024). "Elevated levels of pro-inflammatory cytokines, such as interleukin-1 beta (IL-1β), interleukin-6 (IL-6), and tumor necrosis factor-alpha (TNF-α), have been observed in the blood and cerebrospinal fluid of individuals experiencing migraine attacks." (PMID 39107712, 2024). "During migraine attacks, there are elevated serum levels of IL-10 and TNF-α; moreover, between attacks, TNF-α levels in plasma are higher in children who suffer from migraine compared to those who do not." (PMID 37755358, 2023).